USP17L12 (ubiquitin specific peptidase 17 like family member 12)
Description:
Deubiquitinating enzyme that removes conjugated ubiquitin from specific proteins to regulate different cellular processes that may include cell proliferation, progression through the cell cycle, apoptosis, cell migration, and the cellular response to viral infection.
Tractability: No criterion of Open Targets' tractability assessment is met for any kind of drug.
Gene: Protein-coding gene on chromosome 4 (9,220,152 to 9,221,744, forward strand). Ensembl gene ENSG00000227551.
Subcellular location: Nucleus; Endoplasmic reticulum
Pathways (Reactome):
Metabolism of proteins: Ub-specific processing proteases
Gene Ontology:
Molecular function: cysteine-type deubiquitinase activity
Biological process: regulation of apoptotic process; protein deubiquitination
Cellular component: endoplasmic reticulum; nucleus
Homologues: Paralogues in human: USP17L21 (99% identical), USP17L19 (99% identical), USP17L20 (99% identical), USP17L22 (99% identical), USP17L11 (99% identical), USP17L18 (99% identical), USP17L24 (99% identical), USP17L25 (99% identical), USP17L26 (99% identical), USP17L27 (99% identical), USP17L28 (99% identical), USP17L29 (99% identical), and 59 more.